GAS5 (growth arrest specific 5)
Diseases named in the same sentence as GAS5 in open-access papers (continued):
Sharing a sentence is not in itself a finding about the gene and the disease.
ovarian carcinoma (continued). "Further on, the up-regulation of GAS5 was found to increase both the ratio of G0/G1 arrest and apoptosis in ovarian cancer." (PMID 33076450, 2020). "In epithelial ovarian cancer, the expression of GAS5 is lower than that in the adjacent tissues, and GAS5 inhibits DDP resistance and tumor progression of epithelial ovarian cancer via the GAS5-E2F4-PARP1-mitogen-activated protein kinase (MAPK) axis." (PMID 32771923, 2020). "GAS5 was also found to be down-regulated in epithelial ovarian cancer in another study, where it was related to disease prognosis, in particular." (PMID 33076450, 2020). "In this study, we selected lncRNA-GAS5 to be dramatically down-regulated in ovarian cancer by microarray assay, and then confirmed the low-expression of GAS5 in EOC tissues and OC cell lines." (PMID 31391118, 2019). "Secondly, the clinical sample size in this study can be enlarged, especially in the normal group, and the effect of GAS5 expression level on prognosis in different stages of ovarian cancer can be lucubrated." (PMID 31391118, 2019). "A total of 19 lncRNAs significantly related to prognosis of ovarian cancer were obtained using univariate Cox regression analysis, and the 5 prognostic signature lncRNAs GAS5, HCP5, PART1, SNHG11, and SNHG5 were used to establish a risk assessment system." (PMID 31182053, 2019). "In the present study, we showed that lncRNA GAS5 plays a protective role ovarian cancer by inflammasome formation." (PMID 29229673, 2018). "Knockdown and overexpression of lncRNA GAS5 were design to further study the role of lncGAS5 in ovarian cancer cells." (PMID 29229673, 2018). "The expression level of GAS5 was significantly down-regulated in ovarian cancer tissues as compared with the corresponding adjacent normal tissues." (PMID 29229673, 2018). "For example, a low level of lncRNA GAS5 produced a poorer overall survival rate against ovarian cancer." (PMID 30030896, 2018). "In contrast, exogenous overexpression of lncRNA GAS5 in ovarian cancer cells inhibited proliferation, colony formation, and apoptosis in ovarian cancer cells." (PMID 29229673, 2018). "In the present study, we explored the cellular mechanism and clinical value of lncRNA GAS5 in ovarian cancer." (PMID 29229673, 2018). "Decrease in lncRNA GAS5 expression resulted in increased cell proliferation and colony formation and reduced ovarian cancer cell apoptosis." (PMID 29229673, 2018). "GAS5 was shown to be downregulated and characterized to inhibit cell proliferation, migration and invasion and promote apoptosis in epithelial ovarian cancer cells." (PMID 27992375, 2017). "In the DisLncPri predicting result list, we found 4 novel lncRNAs in top 20 (GAS5 at 1, MALAT1 at 4, MEG3 at 6 and HOTAIR at 9) that were recently associated with ovarian cancer." (PMID 27992375, 2017). "The effect of altered GAS5 on ovarian cancer cell phenotypes was investigated in vitro and in vivo." (PMID 39337410, 2024). "LncRNA GAS5 may therefore be a potential indicator of poor prognosis in ovarian cancer and a therapeutic target." (PMID 39337410, 2024). "Thus, by first suppressing the expression of miR-21 and then upregulating the expression of SPRY2, GAS5 inhibits the proliferation of ovarian cancer cells." (PMID 39337410, 2024). "In ovarian cancer cells, high expression levels of GAS5 promote apoptosis." (PMID 39337410, 2024). "In contrast, GAS5 overexpression inhibits ovarian cancer cell proliferation in vitro and in vivo." (PMID 39337410, 2024). "Additionally, low GAS5 expression was significantly associated with poor overall survival (OS) and progression-free survival (PFS) in ovarian cancer patients through Kaplan–Meier analyses." (PMID 37639158, 2023). "Our results revealed that GAS5 showed a tumor suppressor function in ovarian cancer." (PMID 37639158, 2023).
ovarian carcinoma (continued). "We speculated that GAS5 inhibited the stabilization of hnRNPK protein which impacted the expression of hnRNPK and the development of ovarian cancer due to the exon 12 of GAS5." (PMID 37639158, 2023). "In ovarian cancer, the levels of lncRNA GAS5 was downregulated, while lncRNA HOTTIP was upregulated, indicating that lncRNA GAS5 and HOTTIP may be the futuristic diagnostic biomarkers." (PMID 36059539, 2022). "Not only did they determine the repressed expression of lncRNA GAS5 in ovarian cancer tissues, but also they used lncRNA GAS5 overexpression and depletion models to identify that lncRNA GAS5 triggers the formation of inflammasome, thus leading to pyroptosis both in vivo and in vitro." (PMID 35198448, 2022). "Notably, overexpression of lncRNA GAS5 elevated the cisplatin sensitivity in ovarian cancer cells and in mice." (PMID 36105363, 2022). "LncRNA GAS5 expression in SKOV3/DDP cells has been found to be significantly reduced compared to that in drug-sensitive cells, and it has been reported that GAS5 can sensitize ovarian cancer cells to DDP by leading to G0/G1 cell cycle arrest and increasing apoptosis." (PMID 34512721, 2021). "In contrast, growth arrest-specific 5 (GAS5) is an lncRNA that exerts a tumor-suppressive function in ovarian cancer through sponging miRNAs such as miR-21, and by facilitating the E2F4-mediated transcriptional repression of poly (ADP-ribose) polymerase 1 (PARP1)." (PMID 34681900, 2021). "Ovarian cancer is a grave gynecological tumor and there are not many studies concerning the role of GAS5 in it or its association with chemoresistance in this tumor." (PMID 33076450, 2020). "However, similar to other gynecological tumors, it seems that all studies converge to the conclusion that GAS5 acts as a tumor suppressor in ovarian cancer, as well." (PMID 33076450, 2020). "As an intervention therapy against the low-expression of GAS5, rapamycin may take part in the combination therapy of ovarian cancer, but need more investigation." (PMID 31391118, 2019). "There are some limitations of our study, first of all, whether rapamycin can affect the apoptosis of ovarian cancer cells by targeting GAS5 expression and how to participate in GAS5 target gene (E2F4 or PARP1) regulation need to be further studied." (PMID 31391118, 2019). "Here rapamycin might be considered as an intervention therapy against ovarian cancer progression by regulating GAS5 expression, and our findings may lay a theoretical foundation for the development of combination therapy of ovarian cancer." (PMID 31391118, 2019). "And we proposed that Rapamycin might be used to offset the low expression of GAS5 in ovarian cancer." (PMID 31391118, 2019). "p21 has been shown to be a functional target of GAS5 in ovarian cancer cell lines." (PMID 31534503, 2019). "We detected the RNA expression of lncRNA GAS5 in patients diagnosed with ovarian cancer." (PMID 29229673, 2018). "Importantly, our results showed that expression of lncRNA GAS5 in 20 patients with ovarian cancer was lower in cancer tissues as compared with adjacent normal counterparts." (PMID 29229673, 2018). "Taken together, our results indicated that lncRNA GAS5 could inhibit tumor progression by promoting ovarian cancer cell apoptosis and pyroptosis." (PMID 29229673, 2018). "Thus, we attempted to detect the expression of GAS5 in clinical ovarian cancer sample and investigated the effect of altered expression of GAS5 on ovarian cancer cells." (PMID 29229673, 2018). "However, limited information is available on the role and function of lncRNA GAS5 in ovarian cancer." (PMID 29229673, 2018). "The present study explored the role of lncRNA GAS5 in ovarian cancer." (PMID 29229673, 2018). "Our study showed that lncRNA GAS5 was decreased in human ovarian cancer tissues, thereby indicating that GAS5 may play a role as tumor suppressor and an indicator of poor prognosis in ovarian cancer patients." (PMID 29229673, 2018).
ovarian carcinoma (continued). "Furthermore, exogenous GAS5 suppressed proliferation, enhanced apoptosis, and decreased migration, and the invasion of ovarian cancer cells." (PMID 27664137, 2017). "Thus, the GAS5/miR-21/SPRY2 signaling pathway could be a viable target for treatment in ovarian cancer." (PMID 39337410, 2024). "However, whether GAS5 affects the occurrence and development of ovarian cancer through interaction with protein remains unclear." (PMID 37639158, 2023). "Besides, overexpression of GAS5 increased the accumulation of ovarian cancer cells in the G1 phase." (PMID 37639158, 2023). "The lncRNA GAS5 may regulate the expression of PARP1 by recruiting the transcription factor E2F4 to its promoter, affecting the activity of the MAPK signalling pathway, promoting apoptosis and causing G0/G1 arrest in ovarian cancer cells." (PMID 35725373, 2022). "In addition, because of its 5’TOP structure, the expression of GAS5 in cytoplasm could be elevated by translation inhibitor Rapamycin, and this intervention may be used to offset the low expression of GAS5 in ovarian cancer." (PMID 31391118, 2019). "Decreased expression of GAS5 could lead to ovarian cancer development." (PMID 29229673, 2018). "Several lncRNAs like ZFAS1, MALAT1, H19 have been shown to increase resistance to cisplatin while lncRNA like GAS5, NEAT1 lower cisplatin resistance in ovarian cancer cells." (PMID 39912983, 2025). "The lncRNA GAS5 sponges miR21, alters PARP1 expression modulating cell proliferation in ovarian cancer cells." (PMID 39912983, 2025). "Here, we review NEAT 1, SOX21-AS1, H19, 74 LOXL1-AS1, MAFG-AS1, GAS5 and LINC0015 long non-coding RNAs because of their involvement in ovarian cancers." (PMID 39337410, 2024). "We first analyzed GAS5 expression in ovarian cancer according to the CSIOVDB database and found that GAS5 was downregulated in ovarian cancer compared with that in ovarian surface epithelial." (PMID 37639158, 2023). "Taken together, our data showed that GAS5 suppressed tumor growth and enhanced the sensitivity of cisplatin (DDP) in ovarian cancer." (PMID 31391118, 2019). "In this study, we confirmed the low-expression of lncRNA GAS5 in EOC tissues and OC cell lines, ascertained its tumor suppressor gene like role and discovered its sensitization function of cisplatin in ovarian cancer." (PMID 31391118, 2019). "Five ovarian cancer cell lines SKOV3, OVCAR-3, A2780, 3AO, and human ovarian epithelium cells (IOSE25) were used to detect the relative expression of lncRNA GAS5 using qRT-CPR." (PMID 29229673, 2018). "Other lncRNAs have also been shown to be associated with ovarian cancer development and metastasis, including HOTAIR, H19, GAS5, and UCA1; however, to date, little was known about linc-ROR in ovarian cancer." (PMID 29050257, 2017). "In ovarian cancer, it has been shown that the lncRNAs HOTAIR, MALAT1, LINC01127, AB073614, ElncRNA1 and ANRIL modulate the PI3K pathways, while LncRNA HOST2 GAS5, TUBA4B modulate the RAS pathway and lncRNAs TUG1, HOXD-AS1, SNHG20 and EBIC modulate the Wnt/β-catenin pathway." (PMID 39912983, 2025). "GAS5 has been reported to function as a tumor suppressor-like gene, that can block ovary cancer progression, whereas UCA1 serves as a potential novel biomarker and therapeutic target for ovarian cancer." (PMID 35901079, 2022). "However, numerous lncRNAs have been found to inhibit the cisplatin resistance in ovarian cancer, such as LINC01508 and GAS5." (PMID 36105363, 2022). "Further research showed that GAS5 could inhibit DDP-resistance and tumor progression of ovarian cancer via the GAS5-E2F4-PARP1-MAPK axis." (PMID 34512721, 2021). "By searching related literature and databases, about 30% lncRNAs have been verified to play roles in the regulation of proliferation, invasion, and migration of ovarian cancer cells, including ZFAS1, SNHG1, GAS5, EMX20S, GIHCG, TP53TG1, EPB41L4A-AS1, SNHG8, SNHG6, and HCP5." (PMID 33519912, 2020).
ovarian carcinoma (continued). "Moreover, MALAT1, NEAT1, GAS5, H19 and XIST have been experimentally validated to be ovarian cancer-related lncRNAs, which were identified as hubs that connect 26, 15, 22, 20 and 9 modules in OV dataset, respectively." (PMID 30732558, 2019). "Growth arrest-specific transcript 5 (GAS5) is a 651-nucleotide long non-coding RNA (lncRNA) located on chromosome 1q25.1, commonly downregulated in various human cancers, including breast, lung, prostate, colorectal, melanoma, bladder, liver, stomach, cervical, thyroid and ovarian cancers." (PMID 40451925, 2025). "Splice forms alter the oncogenic and tumour role of GAS5 in malignant tumours, and the role of non-coding RNA, SNHG17 in ovarian cancer needs to be investigated." (PMID 37091785, 2023).
diabetes (38 papers, 2017 to 2025). "The observed downregulation of gas5 across multiple tissues further implicates its potential role in the systemic metabolic alterations associated with diabetes." (PMID 40332318, 2025). "Individuals with diabetes had lower serum levels of GAS5 expression; a GAS5 value of <10 ng/μL is associated with a twelve-fold increased risk of developing diabetes." (PMID 39458514, 2024). "This suggested that a combination of GAS5 and miR-21 has higher diagnostic efficacy for diabetes than lncRNA GAS5 and miR-21 alone, while miR-21 alone has the highest diagnostic efficacy for DN." (PMID 37821982, 2023). "GAS5 lncRNA is decreased in the serum of patients with diabetes and individuals with low GAS5 levels are more susceptible to develop diabetes, as its reduction decreases the insulin secretion and increases the β-cell dysfunctionality." (PMID 37670346, 2023). "Meanwhile, knockdown GAS5 expression promoted the transition of M1-M2 macrophages to rescue impaired wound healing caused by diabetes." (PMID 36035490, 2022). "In another study, GAS5 was found to be associated with the promoter element of the insulin receptor, altering its expression in patients with type 2 diabetes mellitus." (PMID 35155450, 2021). "For example, growth arrest specific 5 (GAS5) has been suggested as a prognostic biomarker, as reduced GAS5 levels increase the risk of developing diabetes." (PMID 34299336, 2021). "The decrease in expression level of Gas5 is related to insulin resistance; it is a high risk factor for diabetes." (PMID 34526965, 2021). "Several recent studies have reported that the plasma levels of GAS5 are associated with diabetes and coronary artery disease." (PMID 32413995, 2020). "Decrease in circulating lncRNA GAS5 is positively associated with diabetes and offered a new tool for identifying people at risk of diabetes." (PMID 31631065, 2019). "Reduced serum levels of GAS5 are related to diabetes; therefore, serum GAS5 levels combined with other parameters may be used for identifying people at high risk of diabetes more accurately." (PMID 33526014, 2021). "Gas5 in peripheral blood is associated with diabetes incidence rate." (PMID 34526965, 2021). "Third, other environmental risk factors, including the rates of smoking, diabetes, hypertension, hyperlipidaemia, and hypercholesterolemia, might have complicated the correlation between GAS5 variants and IS." (PMID 33937403, 2021). "Therefore, GAS5 plays an important role in diabetes and diabetic vascular complications and may be a new diagnostic target for diabetes." (PMID 35178132, 2022). "The analysis revealed that urinary GAS5, eGFR and hypertension/diabetes history had p-value less than 0.05, indicating a statistically significant association with the occurrence of renal fibrosis after adjusting for confounding factors." (PMID 40685500, 2025). "GAS5 levels are markedly lower in serum samples from individuals diagnosed with type 2 diabetes mellitus (T2DM) and it affects insulin signaling and glucose uptake by binding to UPF1 and regulating insulin receptor expression." (PMID 40563948, 2025). "Conversely, the inhibitory effect of diabetes on GAS5 mRNA expression was markedly reversed by PDB and flavone treatment (DN + P and DN + F groups), as evidenced by 1.9- and 1.7-fold increases, respectively, relative to the DN group." (PMID 40486272, 2025). "Overall, these observations indicated that downregulation of GAS5 expression was indispensable in the DN mice and in HG–induced podocytes, implying that this gene plays a crucial role in diabetes microvascular complications." (PMID 40486272, 2025). "Distinct studies demonstrate elevated circulating GAS5 levels in CHD patients, whereas serum GAS5 is significantly reduced in type 2 diabetes mellitus (T2DM) patients, with parallel downregulation observed in adipocytes from T2DM individuals." (PMID 40563948, 2025).